FOXP3 (forkhead box P3)
Diseases named in the same sentence as FOXP3 in open-access papers (continued):
Sharing a sentence is not in itself a finding about the gene and the disease.
tumor (continued). "In addition to activated CD4+ and CD8+ T cells, CTLA-4 is constitutively expressed on immunosuppressive FoxP3+ Tregs and plays a crucial role in Treg-driven suppression of anti-tumour immunity." (PMID 34299373, 2021). "However, in renal carcinoma, it has been reported that the expression of FoxP3 was higher in tumor-infiltrating Vδ1Tc, compared with Vδ2Tc." (PMID 33532902, 2021). "HIF-1α, which stably exists in the tumor microenvironment, could also facilitate the recruitment of Foxp3+ Tregs by a TGF-β-independent mechanism." (PMID 33746989, 2021). "Although the frequency of Foxp3+ cells in the tumor is decreased in the PD-1 Ab, PD-1KO, and PD-1cKO mice, the suppressive function Foxp3+Tregs might still be enhanced." (PMID 34912335, 2021). "The results are consistent with the initial hypothesis that FoxP3+Treg cells inhibit anti-tumor immunity." (PMID 34654443, 2021). "Indeed, high tumor infiltration of FoxP3+ Tregs is correlated with poor prognosis in many types of cancer." (PMID 33808154, 2021). "Among the SDETFs, Foxp3 is significantly associated with FIGO stage and tumor size." (PMID 33671013, 2021). "Finally, the median value of cells FOXP3+ was 0% in both primary tumor and metastases, and these results are similar to the findings already reported, which generally describe the absence of FOXP3+ in L-BC." (PMID 33691674, 2021). "Moreover, cases with HG tumor budding also displayed reduced numbers of stromal B cells and mature DC concomitantly with increased numbers of stromal FOXP3+ Tregs." (PMID 33806316, 2021). "Therefore, the present work investigated the FOXP3 expression pattern and its correlation with various clinicopathological variables to strengthen its prognostic value and tumor-suppressive property." (PMID 34938323, 2021). "The 10 identified metaclusters were divided into three main groups: (i) senescent and terminally differentiated (metaclusters 6,8,4) or non-tumour responsive (metaclusters 2,5,9,10) (~76.15 ± 9.45%), (ii) exhausted (metacluster 7; 2.71 ± 2.03%) and (iii) Foxp3+ regulatory (~18.53 ± 8.78%)." (PMID 33917832, 2021). "The role of forkhead box protein P3 (FOXP3) in tumor microenvironment (TME) remains controversial." (PMID 34006632, 2021). "Similarly, in a rodent model with an intestine tumor, 12 weeks of treadmill exercise 6 days/week for 1 h/day at 15 m/min with −5% grade reduced tumor growth and decreased FoxP3 expression in intestine tumor cells." (PMID 33808154, 2021). "Tumour immune scores (IS) were generated through a combination of HLA-G, HLA-E, and classical HLA-class I tumour expression and numbers of tumour-infiltrating immune cells expressing FoxP3." (PMID 34361031, 2021). "CTLA4, Tim3, Foxp3, GATA3, CD127, TCRab and TIGIT increased in cluster 17 of CD3+ T cell in patients with LC, of which CTLA4 expressed in tumour CD8 T cells associated with PD‐1‐mediated T‐cell dysfunction and efficacy of the checkpoint block immunotherapy in cancers." (PMID 34841705, 2021). "Foxp3 was mainly present in the nucleus and cytoplasm of tumor cells." (PMID 34566989, 2021). "In addition, there was a positive correlation between B7-H4 expression and the number of Foxp3+ Tregs in the tumor, but an inverse correlation with the number of TILs." (PMID 34943606, 2021). "The presence of the CD4+ T-reg cells (CD4+/FOXP3+) has been linked with poor prognosis in HCC and a reduced response to ICI therapy so decreases in tumour infiltration of CD4+ Treg cells may ease the immunosuppressive environment allowing immune recognition." (PMID 35936114, 2021). "With regard to tumor-infiltrating Tregs, their prognostic significance in the context of CRC is well established; a high infiltration of Foxp3+ Tregs is frequently associated with improved OS after surgical resection, although their association with DFS is less clear." (PMID 33527196, 2021). "The prognostic value of FoxP3+ Tregs in ‘tumor microenvironment’ remains controversial." (PMID 34086741, 2021).
tumor (continued). "FOXP3-positive cells, mainly Tregs, are generally thought to disrupt anti-tumor immunity." (PMID 34804034, 2021). "The percentage of CD4+ FoxP3+ T cells was lower in the tumors treated with STINGa, implying that tumor-infiltrating Tregs might lose FoxP3 expression following STINGa treatment." (PMID 35008305, 2021). "Hence an increase in intratumoral pDCs was often observed with simultaneous increase of Foxp3+ regulatory T cells in the same lesion and positively correlated with tumor vascular density." (PMID 33868318, 2021). "In addition, TCGA dataset analysis also showed a higher positive correlation coefficient between CCL5 and FOXP3 expression in HCC with tumor recurrence compared to cases with good prognosis (r = 0.49 vs 0.13)." (PMID 34215748, 2021). "Therefore, we infer that in our study most cases were predominantly CD8+ infiltrated, and the pro-tumor effect from FoxP3+ cells is mainly due to the suppression of immune effector cells." (PMID 35049245, 2021). "In addition, they showed that tumor-derived Gal-1 promotes an immunosuppressive breast cancer microenvironment by increasing the frequency of CD4+CD25+ Foxp3+ Treg cells within the tumor, draining lymph nodes, spleen, and lung metastases." (PMID 34680031, 2021). "FOXP3 is considered as an important factor through tumor development." (PMID 34006632, 2021). "We further showed that there was a positive correlation between IDO+ tumor cells and FoxP3+ Tregs." (PMID 34051744, 2021). "It has already been shown that patients with low tumor cells FOXP3 expression and high regulatory T cells count have a significantly worse OS, suggesting that tumor FOXP3 expression could be used as a high-fidelity prognostic potential in NSCLC." (PMID 34484217, 2021). "FOXP3 has a crucial role in Treg cells, suppressing the effect of cytotoxic T cells on tumor cells." (PMID 34150844, 2021). "The IL2RB-biased engineered cytokine NKTR-214 significantly increases the ratio of CD8 CTLs to immunosuppressive CD4 FOXP3 T-regulatory cells, creating a potent anti-tumor environment, while also increasing the expression of immune-checkpoints such as CD274 (PDL1)." (PMID 33928242, 2021). "Additionally, GO-Y030 treatment resulted in a significantly reduced Foxp3+ Tregs population in tumor-infiltrating lymphocytes compared with that from DMSO treatment." (PMID 34248973, 2021). "Helios-deficient tumor-infiltrating Treg cells produced significant amounts of proinflammatory cytokines (TNF-a, IFN-γ), displayed a nonanergic phenotype, reduced immunosuppressive activity and profoundly restrained Foxp3 and CD25 expression." (PMID 34539668, 2021). "Since the 20 peptides identified from the biopanning assay using the phage-displayed peptide library could bind to any part of FOXP3, it could be postulated that some of them might have an impact on the tumor-suppressor activity of FOXP3." (PMID 33671179, 2021). "The average of Foxp3+ T cell numbers from 10 random tumor areas was 48.5 /mm2." (PMID 34758773, 2021). "Because the characteristics of the immune microenvironment in MNT and MNCA have not been studied, we investigated the distribution and cell density of infiltrating CD8 (+) T cells, FOXP3 (+) T cells and PD‐1 (+) T cells and the PD‐L1 positivity rate in the tumor cells." (PMID 33819365, 2021). "Increased numbers of FOXP3+ lymphocytes, higher IL17A, lower IL2 and a principal component involving Ki67 and macrophages were independently associated with worse outcome in the tumor compartment." (PMID 33648463, 2021). "Additionally, Mathai’s group discovered that a high Foxp3 +/CD8+TIL ratio was correlated with poor tumor differentiation, high recurrence, poor overall survival, and disease-free survival in post-surgery HCC patients." (PMID 34566989, 2021). "Conversely, no such correlation was evident between FOXP3+ T cell infiltration in intratumoral or tumor-distant normal mucosa and β2M mutation status." (PMID 34125344, 2021).
tumor (continued). "Combined with the inhibitory effects of mir-150 on OC tumorigenesis, we surmise that miR-150-5p/3p may be a key factor in FoxP3-mediated tumor suppression in OC27." (PMID 33723215, 2021). "In the HPD group, there were fewer CD4+ effector T cells and CD8+ cytotoxic T cells (P < 0.010 and P < 0.382, respectively), whereas, there were significantly more regulatory T (Treg) cells co-expressing CD4+ and FOXP3+ in both the tumor and stroma (P < 0.003 and P < 0.015, respectively)." (PMID 33402127, 2021). "We thus examined Foxp3 expression in the tumor-infiltrating Treg to correlate with CD39 expression." (PMID 34407765, 2021). "Similarly, disruption of Ezh2 activity or depletion of Helios in Tregs leads to Foxp3 instability with an increased expression of effector cytokines like IFNγ and TNFα, enhanced anti-tumor immunity, and decreased tumor growth and progression." (PMID 34394124, 2021). "Furthermore, the number of tumor-infiltrating FOXP3+ Treg in tumor tissue increases with tumor progression." (PMID 34569432, 2021). "IDO-positive tumors contained significantly higher amounts of FoxP3+ Tregs (p < 0.0001), IDO+ stromal immune cells (p < 0.0001), and both CD68+ and CD163+ tumor associated macrophages (TAMs) (p-values < 0.0001), compared to IDO-negative tumors (data not shown)." (PMID 34051744, 2021). "Thus, it is likely that the increased CD8+/FoxP3+ ratio, which is considered a measure of anti-tumor immunity, contributes to the anti-tumor effects of REG and REG + aPD1." (PMID 34517894, 2021). "Another study trained a scoring model which identified the presence of FOXP3 and PD-1 in tumor tissue, as well as stromal FOXP3 and CD8 infiltration as predictors of tumor outcomes, with their model effectively differentiating disparate tumor outcomes within the same Enneking stage." (PMID 34067530, 2021). "This type of tumor was characterized by the stromal positivity for PD-L1 and the infiltration of FOXP3+CD4+ T cells, indicating the development of a potentially immunosuppressive stromal microenvironment and partially explaining the worse overall survival of the patients with this type of tumor." (PMID 34885122, 2021). "The relationship between the ratios of TILs FOXP3+ /CD8+, FOXP3+/CD4+ and CD4+/CD8+ and tumor recurrence was analyzed and only high FOXP3+/CD8+ and high FOXP3/CD4 + ratios were found to be associated with a decreased recurrence-free survival (p = 0.02 and p = 0.036, respectively)." (PMID 34952631, 2021). "Compared to traditional IL-2, NKTR-214 does not cause significant amplification of CD4+ Foxp3+ Tregs, and thus, has greater anti-tumor activity and fewer adverse effects." (PMID 33746989, 2021). "In addition, non-statistically significant differences were seen in the frequency of CD4+FoxP3+ T cells and CD11b+Ly6G+ cells in the tumours of pHIFU + ICI-treated subjects compared with controls 48 h after treatment." (PMID 34229458, 2021). "Additionally, the percentage of CD4+FOXP3+ Tregs in tumor tissues exhibited a significant positive association with L1CAM and CCL22 in patients with ESCC." (PMID 33710805, 2021). "Notably, among the TIL subsets, FOXP3 represented an independent marker for prediction of aggressive tumor subgroups in this series." (PMID 34076969, 2021). "Furthermore, a subset of genes expressed by CAFs was found to increase the proportion of CD4+FOXP3+ regulatory T cells (Tregs) creating an immunosuppressive tumour microenvironment that prevent the tumour-reactive immune responses." (PMID 34681023, 2021). "Pearson correlation coefficients were calculated, and the results indicated that BGN presented the strongest correlations with TIIC markers for monocytes (CD86, CD115), tumor-associated macrophages (TAMs) (IL-10, CCL2, CD68), M2 macrophages (CD163, VSIG4, and MS4A4A) and Tregs (FOXP3, CCR8, TGFβ)." (PMID 35096572, 2021).
tumor (continued). "Moreover, both the CF1 and total TI Treg signatures had superior discrimination ability when compared to previously reported tumor Treg markers, such as FOXP3 and ratio-based signatures CCR8:FOXP3 or CCR8:CD3G 12,13." (PMID 34599187, 2021). "Eighteen HCC tumor tissues were stained for TGFβ, αSMA, and FoxP3." (PMID 34769191, 2021). "The anti-tumoral effect was correlated with the generation of CD4+, CD8+ T cells, and CD44+ CD62L- CCR7low CD127low T-effector memory cells, and the reduction of CD4+ CD25+FoxP3+ Tregs, Arg1+ CD11b+ Gr1+, and Arg1+ and CD11b+ Ly6+ myeloid-derived suppressor cell populations within the tumor." (PMID 34957134, 2021). "Additionally, Foxp3+ cells were clearly observed in the intestine of the WT CAC mice during the late stages of tumor progression (Day 76)." (PMID 33919941, 2021). "However, a trend towards decreasing the ratio of intratumoral FoxP3+ cells to CD3+ lymphocytes was observed in doxorubicin-treated tumor-bearing mice." (PMID 34094037, 2021). "IL-32 may promote CD8+ T cell IFNγ expression that enhances the antitumor activity, but at the same time induce CD4+ T cell Foxp3 expression, which could suppress tumor immune response." (PMID 34414188, 2021). "Despite these associations with good prognostic indicators, we were not able to find any statistically significant alterations in the overall survival of the patients, even though high infiltrations of FoxP3+ T lymphocytes in the tumor margins resulted in an increased overall survival of 14 months." (PMID 34440038, 2021). "Indeed, in both cases, almost 30% of CD4+ T-cells are FOXP3+ as compared to the normal levels of FOXP3+ Treg found in the spleen or in the tumor-draining lymph nodes." (PMID 33671179, 2021). "This is inconsistent with the primary hypothesis that FoxP3+Treg cells suppress anti-tumor immunity." (PMID 34654443, 2021). "Interestingly, CD4+ CD25+FoxP3+ Treg cells were decreased in tumor tissues from the B. longum 420 and anti-PD-1 antibody combination and B. longum 420-alone groups compared to the other groups." (PMID 34589578, 2021). "To test whether the colocalisation pattern in adjacent DCIS differs according to T cell subsets, we evaluated the quantitative number, ratio and DCIS immune colocalisation using CD4, CD8 and FOXP3 cells in the IHC dataset of adjacent tumours." (PMID 33649333, 2021). "Proteins within tumour compartments consistent with longer OS included PD-L1 (HR=0.53, p=0.023), FOXP3 (HR=0.5, p=0.026), GITR (HR=0.51, p=0.036), SMA (HR=0.59, p=0.043), while EPCAM (HR=1.7, p=0.045), and CD95 (HR=4.9, p=0.046) expression were associated with shorter OS." (PMID 35083152, 2021). "The average FOXP3+ cell density was lower in peritumoral tissue than in tumor tissue." (PMID 34081621, 2021). "Our results have demonstrated that normal tissue Treg and non-tumor diseased tissue Treg have transcriptomic changes in Foxp3-dependent manners; and tumor spleen Treg and tumor Treg have certain transcriptomic changes in Foxp3 non-collaboration manners with ROS and other 17 specific pathways." (PMID 34084175, 2021). "In tumor immunity, FoxP3+ Treg cells are also related to immune escape." (PMID 33819196, 2021). "Moreover, immune cells in no-pCR cases had significantly (P = 0.016) fewer neighboring FoxP3+CD8+ regulatory T cells compared with tumor tissues with pCR." (PMID 33886505, 2021). "Although a balanced activity in general might be beneficial for the patient, it is too early to say whether Foxp3+ cells substantially regulate anti-tumor responses based on their spatial presence and accumulation in TA-TLSs." (PMID 33803245, 2021). "Tumor-associated monocytic myeloid-derived suppressor cells (MDSCs) possess similar features, such as hyper-expression of ILT3 and ILT4, and can educate CD4+ Foxp3− IL-10+ regulatory T (TR) cells." (PMID 34680058, 2021).
tumor (continued). "The preferential tumor recruitment of Tregs was intrinsic to Tregs since parabiosis experiments between WT and Foxp3-EGFP CCR2-/- mice show that EGFP+ CCR2-/- Tregs which migrated to the tumor tissue represented only 20% of total Treg in both WT hosts and CCR2-/- hosts." (PMID 34804061, 2021). "Another mechanism that prevents T cell infiltration into the tumors relies on the overexpression of Fas ligand (FasL) on TEC surface that causes the selective killing of tumor-specific CD8+ T cells and to the accumulation of FoxP3+ T regulatory (Tregs) cells within the tumors." (PMID 33554861, 2021). "In young mice, stress reduced tumor CD4+FoxP3+ cell infiltration (p<0.03)." (PMID 34604038, 2021). "The location of CD8+ and FoxP3+ T cells in relation to each other as well as the distance from the tumour cells (stromal vs intra-tumoural) could reflect functionality." (PMID 34321074, 2021). "Interestingly, tumor suppressor and T-regulatory functions of FOXP3 seem to be mediated through separate signaling pathways." (PMID 33671179, 2021). "This is antithetical to the evidence that intra-tumor TGFβ is supposed to imprint a tolerogenic phenotype in antigen-presenting cells (mainly dendritic cells), which in turn migrate in peripheral lymphoid tissues to drive FoxP3+ Tregs commitment." (PMID 34769191, 2021). "Furthermore, FOXP3 suppression can inhibit tumor invasion and metastasis via downregulating the angiogenic factor VEGF, the epithelial-mesenchymal transition (EMT), and the Notch1/Hes1 pathway." (PMID 37305162, 2021). "Additionally, activation of PD-1 in naïve CD4+ T cells induces their conversion to immunosuppressive CD4+ FoxP3+ T regulatory cells (Tregs) which, in a juxtracrine and paracrine manner, inhibit anti-tumour immune responses." (PMID 34299373, 2021). "Tumor cells, TAMs, tumor-associated neutrophils (TANs), Tregs, and MDSCs generally secrete TGF-β while express surface PD-L1 that binds with PD-1 on T cells, which all together promote the expression of FoxP3, thus differentiating T cells into GrBhigh iTregs." (PMID 33868318, 2021). "Notably, the present study indicates that high levels of TIL subsets are strongly inversely associated with tumor elastosis, and high counts of CD3+, CD8+, and FOXP3+ lymphocyte subsets are also related to interval detected cancers." (PMID 34076969, 2021). "FOXP3 interacts closely with immune biomarkers on tumor-infiltrating cells in TME." (PMID 34006632, 2021). "In the tumor microenvironment (TME), tumor-induced Foxp3-negative IL-17A+ Th17 cells decline in number at later time points, concomitant with the increase of “ex-Th17” Foxp3+IL-17A- suppressive tumor-associated Tregs." (PMID 34992594, 2021). "Moreover, DHA treatment significantly reduced Foxp3+cells infiltration into tumor tissues and returned to levels similar to those in the wide-type mice." (PMID 34539408, 2021). "Infiltration of CD3+, CD8+, and FoxP3+ cells into the tumor was assessed by immunohistochemistry." (PMID 34094037, 2021). "Whether some FOXP3 expression takes place in non- T cells (i.e., inhibitory transcriptional signaling in expanding tumor cells) in this model is unclear." (PMID 34715561, 2021). "Studies show that FOXP3, a vital factor, restrains cytotoxic T cells from attacking tumor cells." (PMID 33888142, 2021). "Moreover, a large study of 1,420 tumor samples found a significantly higher amount of FOXP3+ tumor-infiltrating Treg in pMMR CRC samples." (PMID 35095898, 2021). "In tumor cells from patients with HBV-associated HCC, PreS2 overexpression could trigger the Foxp3 overexpression." (PMID 34566989, 2021). "In this panel, PD-L1 (immune checkpoint), CD3 (T cells), CD8 (cytotoxic T cells), CD163 (histiocytes/macrophages), and FoxP3 (regulatory T cells) were analyzed in epithelial tumor (CK+) and surrounding stromal (CK-) compartments, respectively, across 3 different tumor types." (PMID 33596250, 2021).